AHR (aryl hydrocarbon receptor)
Diseases named in the same sentence as AHR in open-access papers (continued):
Sharing a sentence is not in itself a finding about the gene and the disease.
colitis (continued). "Mice with knockout for caspase recruitment domain-containing protein 9 (Card9) and DSS-induced colitis showed reduced levels of indole derivative indoleacetic acid and a decreased ability of microbiota to activate AhR." (PMID 38543132, 2024). "To verify that LA must associate with AHR to regulate colitis and the Th17/Treg cell balance, we utilized AHR KO mice and established a colitis model by administering either Pg or Pg + LA." (PMID 38388542, 2024). "The result is supported by previous publications suggesting AKAs modulate inflammation by acting as ligands for AhR signaling in experimental colitis and cancer." (PMID 38167866, 2024). "Further, DIM has been reported to ameliorate the severity of DSS-induced colitis through AhR-dependent regulation of the T-helper 17 (Th17)/Foxp3+ Regulatory T-cell (Tregs) axis, favoring the suppression of pro-inflammatory Th17 activity." (PMID 39337636, 2024). "Therapeutically restoring LA levels in colitis mice challenged with Pg exerts anti-colitis effects by decreasing the Th17/Treg cell ratio in an AHR-dependent manner." (PMID 38388542, 2024). "AHR plays a protective role against autoimmune illnesses such as diabetes, colitis, and experimental autoimmune encephalomyelitis (EAE) by modifying adaptive immunity by controlling the T-cell response at several levels." (PMID 38542367, 2024). "The current study’s findings suggest that AhR plays an important role in regulating mucin synthesis by goblet cells, notably Muc2, in both steady-state and colitis conditions." (PMID 38397081, 2024). "In fact, AhR-knockout studies conducted in mice with dextran sodium sulfate (DSS)-induced colitis, showed higher levels of pro-inflammatory cytokines and increased severity of colitis compared with wild-type mice." (PMID 39517263, 2024). "It modulates the gut microbiota and specifically enriches Alistipes onderdonkii, which can produce 5‐hydroxyindole‐3‐acetic acid, thus activating the aryl hydrocarbon receptor pathway and ameliorating colitis." (PMID 38882491, 2024). "Both I3C and quercetin have demonstrated efficacy in mitigating chronic dextran sulfate sodium (DSS)-induced colitis in C57BL/6 mice through anti-inflammatory mechanisms mediated by the AhR." (PMID 39767818, 2024). "Administration of FICZ, an AhR agonist, markedly alleviated the severity of colitis induced by TNBS, DSS, and T-cell transfer in mice." (PMID 39767818, 2024). "We will also describe the results of preclinical work in mouse models of IBD-like colitis, and of clinical trials in which the therapeutic modulation of AHR function has been tested in IBD patients." (PMID 38674118, 2024). "The key findings from the current report are AhR can regulate IL-22 signaling in specific cell types during colitis to alter the gut microbial profile which have consequential and sex-dependent impacts on disease severity." (PMID 39229279, 2024). "It was demonstrated that IAld ameliorates the inflammatory responses in DSS-induced colitis by reversing the inflammatory responses and reestablishing the function of the intestinal epithelial barrier, in part through AHR activation." (PMID 38542367, 2024). "We here review the evidence supporting the role of AHR in controlling the “physiological” intestinal inflammation and summarize the data about the therapeutic effects of AHR activators, both in preclinical mouse models of colitis and in patients with IBD." (PMID 38674118, 2024). "Lactobacillus acidophilus or its metabolite, indole-3-lactic acid (ILA), was also probed to relieve inflammatory status through AhR in DSS-induced colitis cesarean section offspring." (PMID 39517263, 2024). "Collectively, these results suggest that Lys enhances IDO1 expression to confer protection against DSS-induced colitis via AhR activation." (PMID 38351003, 2024).
colitis (continued). "Previously, our group demonstrated that treatment with UroA enhances gut barrier function, reduces inflammation, and attenuates colitis in murine models in an AHR-dependent manner." (PMID 38193707, 2024). "Intestinal epithelial cells (IECs) are also involved in regulating colitis, so we investigated their AhR-mediated mechanisms in the current report." (PMID 38397081, 2024). "There is also evidence that microRNA 124, which sustains IBD-like colitis in mice, can contribute to the reduced expression of AHR in intestinal epithelial cells of CD patients." (PMID 38674118, 2024). "Another significant finding in the current report was that AhR in IECs was essential in I3C-mediated protection against DSS-induced colitis, which was found to be the case in both male and female mice." (PMID 38397081, 2024). "In conclusion, our findings demonstrate that DIM consumption reduces the severity of DSS-induced colitis and affects the formation, size, and T-cell density of TLTs in a manner dependent on the function of AhR in the intestinal epithelium." (PMID 39337636, 2024). "To confirm that intragastric administration of Pg modulates the Th17/Treg cell imbalance and then mediates colitis via the LA-AHR metabolic pathway, we administered Pg to WT and AHR KO colitis mice." (PMID 38388542, 2024). "Using in vivo and in vitro approaches with WT and conditional AhR KO mice under colitis conditions, AhR was shown to affect production of Muc2 after stimulation with an AhR ligand (I3C), and this appeared to be independent of IL-22." (PMID 38397081, 2024). "Ginger ELNs have been shown to mitigate colitis by promoting the colonization of Lactobacillus rhamnosus and producing ligands for the aryl hydrocarbon receptor via endogenous miRNAs." (PMID 38542448, 2024). "In summary, the TCM SH is effective at improving DSS‐induced colitis through, at least partially, enriching A. onderdonkii to elevate the microbial metabolite 5HIAA, thereby activating AhR signaling." (PMID 38882491, 2024). "Consistently, restoring LA levels in colitis mice challenged with Pg decreases the Th17/Treg cell ratio in an AHR-dependent manner, thus leading to the attenuation of mucosal inflammation." (PMID 38674118, 2024). "WT or AHR−/− mice were gavaged with fresh Pg or Pg+LA every 2 days starting 7 days before the establishment of the colitis model and continuing until the end of DSS administration." (PMID 38388542, 2024). "By controlling the T-cell subpopulation and cytokine profile in dextran sodium sulfate (DSS)-induced colitis, AHR can significantly protect against IBD." (PMID 38542367, 2024). "In colitis mice, pharmacological activation of the AhR can improve the pathological symptoms of intestinal inflammation, while AhR knockout increases susceptibility to intestinal inflammation." (PMID 39334766, 2024). "In this context, many studies have documented the benefit of AHR activators in the preclinical models of IBD-like colitis, and some AHR-related compounds have already been tested with success in IBD patients." (PMID 38674118, 2024). "Our findings suggest that DIM affects the immunological landscape of TLT formation during DSS-induced colitis in a manner contingent on AhR expression in IECs and biological sex." (PMID 39337636, 2024). "In the current study, we continued using I3C administration to determine AhR-mediated effects on colitis and regulation of the gut microbiome with focused attention on IL-22 production." (PMID 39229279, 2024). "UroA has recently been shown to reduce inflammation, enhance gut barrier function, and attenuate colitis in murine models in an aryl hydrocarbon receptor (AHR)-dependent manner." (PMID 38193707, 2024). "Lactobacillus reuteri is another strain that significantly modulates AhR to alleviate colitis symptoms." (PMID 39517263, 2024). "According to our review, the administration of specific probiotic strains has been shown to alleviate colitis symptoms in animal models through AhR activation." (PMID 39517263, 2024).
colitis (continued). "Consistently, in the T-cell transfer colitis model, treatment of colitic mice with AhR activators attenuates the mucosal inflammation induced by wild-type T cells but does not influence colitis induced by Smad7 Tg T cells." (PMID 36714553, 2023). "We show here that mice harboring a DNA-binding deficient AHR, which is incapable of binding to AHREs, exhibit a similar sensitivity to DSS-induced colitis as Ahr−/− mice." (PMID 36519841, 2023). "Mice with a CD11c-Cre-mediated specific deletion of AhR in DCs suffer as much from DSS-induced colitis as AhR-/- mice." (PMID 36875083, 2023). "Baicalin, isolated from Radix scutellariae, is a novel AHR ligand that restores the balance of Th17/Treg cells via AHR to alleviate colitis." (PMID 37179416, 2023). "A role of the AHR/miR-132/212 axis has been established in murine models of colitis and of experimental autoimmune encephalomyelitis." (PMID 37696456, 2023). "Two Bifidobacterium bifidum strains, FL-276.1 and FL-228.1, were reported to ameliorate DSS-induced colitis by promoting the AHR pathway, which safeguards the barrier function." (PMID 37942478, 2023). "Lactobacillus reuteri can prevent DSS-induced colitis in mice via tryptophan metabolites such as indole 3-aldehyde, an AHR ligand that activates AHR and enhances IL-22 production." (PMID 37304260, 2023). "Inhibition of AhR counteracted the synergistic effects of the combined treatment, either on the severity of colitis or mRNA expressions in mice with Salmonella colitis." (PMID 36672703, 2023). "In mouse models of intestinal inflammation, AHR activation significantly improves, while its loss or the reduction of its endogenous ligand levels exacerbates dextran sulfate sodium (DSS)-induced colitis and bacterial-induced mucosal inflammation." (PMID 36519841, 2023). "Another study investigated the constitutive deletion of IEC AhR in acute DSS-induced colitis and also observed a worsened inflammatory response compared to WT mice." (PMID 38068838, 2023). "Accordingly, AHR agonists are capable of ameliorating colitis in mice, while AHR antagonists enhanced the severity of colitis." (PMID 37942478, 2023). "AHR activation by bilirubin suppresses experimental colitis, which indicates that bilirubin exerts an AHR-dependent anti-inflammatory effect." (PMID 37179416, 2023). "Previous studies have demonstrated that another tryptophan metabolite, 3-IAld, ameliorates conditions such as EAE and colitis in an AhR-dependent manner." (PMID 37836434, 2023). "Galangal ameliorated colitis in mice by activating AHR, upregulating Foxp3 expression, and restoring Th17/Treg balance." (PMID 37179416, 2023). "To understand the mechanisms of dietary I3C in protection against colitis, we first evaluated AhR activation by +I3C diet by assessing mRNA levels of the AhR target gene, CYP1A1." (PMID 38068838, 2023). "There is increasing interest in the role of acyl hydrocarbon receptor (AhR) on colitis and innate immunity." (PMID 36672703, 2023). "Specifically, FICZ, as an endogenous ligand of AHR, reduces epithelial cell-derived IL-7 expression, concomitant with the amelioration of experimental colitis by reducing the frequency of activated IELs." (PMID 37179416, 2023). "Another potent AHR agonist IPyA has exhibited remarkable anti-inflammatory effects in experimental colitis models through raised colonic IL10-positive T cells and lessening the pro-inflammatory Th1 cytokines." (PMID 37942478, 2023). "In contrast, treatment of mice with an AhR antagonist enhanced the severity of inflammation in trinitrobenzene sulfonic acid-induced colitis." (PMID 36672703, 2023). "Berberine, Shenling Baizhu San, Gegen Qinlian decoction (GQD), and baicalein can greatly prevent the intestinal barrier and inflammation in the animal colitis model induced by DSS by regulating the AHR–microbiota axis." (PMID 37942478, 2023).
colitis (continued). "Lactobacillus bulgaricus strain OLL1181 alleviated DSS-colitis by activating AHR signaling and increasing the expression of CYP1A1." (PMID 37179416, 2023). "The heat shock protein (HSPA8) in mulberry bark EVs can activate aryl hydrocarbon receptor (AHR)-mediated signaling in mice to prevent DSS-induced colitis." (PMID 37759813, 2023). "For instance, Akkermansia muciniphila, a promising probiotic, protects against colitis via activating AHR-Trp signaling." (PMID 37942478, 2023). "As a potential AHR activator, alpinetin regulates Treg differentiation, thereby reducing the symptoms of colitis." (PMID 37179416, 2023). "Studies have shown that indole and its derivatives are major ligands for aryl hydrocarbon receptor (AhR) that induce AhR activation, thereby maintaining intestinal homeostasis, inhibiting pathogen infection, and improving colitis symptoms." (PMID 38032415, 2023). "In this study, MBELNs were used to treat DSS-induced colitis and resulted in significant improvement against gut-related inflammatory disease via the aryl hydrocarbon receptor (AhR)/constitutive photomorphogenic homolog subunit 8 (COPS8) pathway." (PMID 38260737, 2023). "To verify if the beneficial effect of I3C against DSS-induced colitis depended on AHR expression in intestinal epithelial cells, we generated intestinal epithelial-specific AHR knockout mice (villincreAhrfl/fl) and repeated our DSS experiments." (PMID 37669965, 2023). "Mice with reduced AhR activity display increased sensitivity to colitis, intestinal candidiasis, and alcoholic liver disease." (PMID 36894983, 2023). "In the colitis model, AhR knockout mice show more severe symptoms and higher expression of proinflammatory cytokines than WT mice." (PMID 36966295, 2023). "We observed that dietary pectin prevented the development of C. difficile-induced colitis, whereas inulin promoted its development, probably at least in part by promoting the activation of the AhR pathway." (PMID 36439215, 2022). "The Trp metabolite Iald can activate aromatic hydrocarbon receptor (AHR) and induce the expression of interleukin-22 (IL-22) to improve the intestinal barrier and alleviate colitis in mice." (PMID 36238574, 2022). "Propionibacterium freudenreichii ET-3 produces the precursor of vitamin K2, 1,4-dihydroxy-2-naphthoic acid (DHNA), which activates the aryl hydrocarbon receptor (AhR) to ameliorate colitis and modulate gut microbiota." (PMID 36014889, 2022). "Previously, we showed that UroA-mediates gut barrier protective, anti-inflammatory and anti-colitis activities in an AhR-dependent manner." (PMID 36159798, 2022). "Recent studies have shown that the level of IAA is decreased in DSS-induced colitis mouse and the strains capable of metabolizing tryptophan or AHR agonist can inhibit intestinal inflammation." (PMID 35185872, 2022). "We next determined the role of the AhR pathway in the pectin treatment of C. difficile-induced severe colitis." (PMID 36439215, 2022). "Since PARP7 is a negative regulator of AHR and IFN-I, and loss of PARP7 expression increases both AHR and IFN-I signaling, we used a DSS-induced colitis model to investigate the effect of PARP7 loss on DSS-induced intestinal inflammation." (PMID 35055106, 2022). "The activity of IL-10R1 in the epithelium of an AhR is modulated by IPA and IAld, which has been linked to protective effects in colitis models and improves epithelial wound healing." (PMID 35784338, 2022). "The AhR-miR-212/132 axis has also been shown to promote intestinal inflammation within DSS-induced colitis mice via induction of Th17 cells and downregulation of Il-10-producing T cells." (PMID 35626744, 2022). "B. bifidum administration played a positive role in increasing the contents of endogenous AhR ligands, which enhanced AhR activity to exert anti-inflammatory effects in DSS-induced colitis mice." (PMID 36501169, 2022).
colitis (continued). "In summary, we showed that UroA-mediated protective activities against colitis dependent upon expression of CYP1A1 in addition to AhR." (PMID 36159798, 2022). "They highlighted the critical requirement for aryl hydrocarbon receptor (AhR)-nuclear factor erythroid 2-related factor 2 (Nrf2) pathways in urolithin A colitis protective activity." (PMID 35204135, 2022). "The enhanced level of CYP1A1 also indicated the activation of AHR in DSS-induced colitis mouse model." (PMID 35935130, 2022). "These indole metabolites are agonists of the aryl hydrocarbon receptor (AhR), with potential anti-inflammatory properties against colitis." (PMID 36662189, 2022). "Lactobacillus strains were found to efficiently metabolize Tryptophan to its derivatives which act as aryl hydrocarbon receptor (AhR) ligands in the colitis mouse model." (PMID 36776218, 2022). "In contrast to dietary- and gut microbe-derived AhR ligands that mediate intestinal homeostasis, oxazalone has been shown to induce AhR-dependent colitis following downregulation of anti-inflammatory factors (i.e., Il-10) in mouse models." (PMID 35626744, 2022). "Tryptophan metabolites produced by intestinal microflora during induction of colitis by bacterial infection in mice are known to play a protective role in the pathogenesis of the disease through AhR activation, which enhances IL-22 secretion." (PMID 35463998, 2022). "In this section, a significantly higher expression of AHR in the colonic tissue of DSS-induced colitis mice was found among mice in the RSV+Li01 group compared to any other groups (P < 0.0001)." (PMID 35935130, 2022). "Recently, we demonstrated that the microbial metabolite Urolithin A (UroA) mitigates colitis through its gut barrier protective and anti-inflammatory activities in an AhR-dependent manner." (PMID 36159798, 2022). "Nonetheless, it is imperative to take note that UroA or UAS03 mediated protection against colitis requires AhR-Nrf2 pathways." (PMID 36079752, 2022). "AhR −/− mice exhibited severe inflammatory parameters in DSS-induced colitis and produced high levels of proinflammatory cytokines, suggesting that the function of AhR in the intestine is protective." (PMID 36144406, 2022). "A previous study demonstrated that L. reuteri improved the outcomes of colitis, but AhR inhibition reversed this improvement." (PMID 35727038, 2022). "FMT alleviates DSS-induced colitis in mice through increasing the secretion of anti-inflammatory cytokines by activating AhR signaling." (PMID 35626744, 2022). "These indole derivatives can act on pregnane X receptors (PXR) and AhR and have a certain inhibitory effect on inflammatory diseases such as colitis, arthritis, steatohepatitis, ankylosing spondylitis, and obesity —consistent with our experimental results." (PMID 36238574, 2022). "In contrast, here, we show that the loss of PARP7, which also functions as an AHR repressor, reduced inflammation and improved symptoms of DSS colitis." (PMID 35055106, 2022). "AHR activation significantly improves, while its loss exacerbates, dextran sodium sulphate (DSS)-induced colitis, a model of IBD." (PMID 35055106, 2022). "Data from mouse models and patients with Inflammatory Bowel Disease (IBD) suggest that AhR activation exerts a preventive effect on the development of colitis." (PMID 35463998, 2022). "Plant-derived flavonoids, such as alpinetin, have demonstrated efficacy against colitis following direct AhR activation and immunomodulation via promotion of Treg differentiation." (PMID 35626744, 2022). "Our group demonstrated that treatment with AhR ligand UroA upregulated tight junctional proteins, blocked inflammatory cytokines and mitigated chemical-induced colitis in mouse models in an AhR-dependent manner." (PMID 36159798, 2022). "In particular, intestinal AHR expression is found to be significantly diminished in IBD patients, and increased activation of AHR is shown to suppress inflammation in mice of experimental colitis." (PMID 35734371, 2022).